FOXO1 (forkhead box O1)
Diseases named in the same sentence as FOXO1 in open-access papers (continued):
Sharing a sentence is not in itself a finding about the gene and the disease.
tumor (continued). "Kaplan-Meier estimate and the log-rank test showed that patients with a pJNK-negative (JNK inactive) and pFOXO1-negative (FOXO1 active) tumor had significantly worse outcome than those with other combinations (P < 0.001)." (PMID 27268017, 2016). "Tumor cells with cytoplasmic staining regardless of the nuclear staining were considered to exhibit FOXO1 inactivation." (PMID 27268017, 2016). "Among tumor cells, chronic mTORC2 inhibition may be insufficient to prevent PI3 kinase pathway hyper-stimulation, and hyper-phosphorylation of the Akt target, FOXO1/3." (PMID 26295809, 2015). "Further, FoxO1-negative cells formed tumor spheres in culture and developed tumors after serial adoptive transplantation into NOD/SCID mice, while the FoxO1-positive cells did not." (PMID 26068418, 2015). "As such, E2F1/FOXO1 apoptotic and tumor suppressive functions are disabled during normal growth, and in emerging tumors, by the coordinated signaling of the PI3KCA and AKT, which directly disables FOXO1 function." (PMID 25907958, 2015). "Although fluorescence in situ hybridization (FISH) studies revealed FOXO1 (FKHR) gain on chromosome 13q14.11 in 75% of the tumor cells, there was no PAX-FOXO1 translocation." (PMID 25405050, 2014). "However, the expression of some antioxidant genes regulated by FOXO1 does not fully explain the effect of FOXO1 on ROS, which is favorable for tumor cell survival." (PMID 41124013, 2025). "Of note, expression of DNMTs was found to be lower in alveolar RMS tumours (predominantly FP) compared with embryonal RMS tumours (generally FN), and thus we propose that PAX3::FOXO1 may contribute to this expression difference and thereby influence the DNA methylation pattern." (PMID 39812007, 2025). "Nuclear FoxO1 acts as a transcriptional repressor to downregulate JAK1/JAK2 expression, leading to reduced STAT3 phosphorylation at Tyr705, as demonstrated by Western blot and immunohistochemistry, which effectively disrupts a key survival pathway in hypoxic tumor cells." (PMID 40806463, 2025). "In addition, overexpression of FOXO1 or manipulation of T cell metabolism by targeting isocitrate dehydrogenase 2 (IDH2) has been shown to facilitate the generation of memory-like CAR-T cells and improve their anti-tumor activity in vivo." (PMID 40755764, 2025). "Indeed, FOXO1-expressing CAR T cells maintained a less-differentiated state after activation followed by one week of rest, or when CAR T cells were exposed to tumour cells over a period of three weeks." (PMID 38600376, 2024). "As FOXO1, ID3 and TCF7 contribute to the formation of memory T cells that home to secondary lymphoid tissues, we investigated whether CAR T cells overexpressing transcriptional regulators would exhibit enhanced trafficking to tumour dLNs." (PMID 38600376, 2024). "Consistent with the results from the Foxo1Rictor double-KO studies, both c-MYC/FOXO1AAA and c-MYC/pT3-EF1α mice developed a high tumor burden and had to be euthanized by 6–9 weeks after injection, suggesting that activated FoxO1 did not improve the survival of c-MYC mice." (PMID 39325536, 2024). "With FISH analysis the tumor was FOXO1 and EWSR1 break negative." (PMID 35856126, 2023). "Evaluation of miR-182-5p, Cyld and Foxo1 expression levels in peritumor vs. tumor hepatic tissues (GSE22058 datasets), based on the GEO2R tool, demonstrated not only significant miR-182-5p upregulation, but also concomitant Cyld and Foxo1 downregulation in cancer samples." (PMID 37298191, 2023). "However, CD276 (B7-H3) and FoXO1 expression seem not to be directly involved in the acquisition and/or maintenance of tumor stem cell characteristics in vitro." (PMID 36901916, 2023). "However, according to the post-transcriptional regulation activity of miRNAs, immunoblot analysis confirmed overall Cyld and Foxo1 protein downregulation in tumor compared to adjacent non-tumor samples." (PMID 37298191, 2023).
tumor (continued). "Thus, tumor growth inhibition by Rbx1‐deletion is also likely attributable to accumulation of cell cycle inhibitor p21 and apoptosis inducer Foxo1, but not p27 and Nrf2." (PMID 37470067, 2023). "Abnormal cells that would normally undergo apoptosis may instead survive in the absence of FOXO1, which results in tumor expansion." (PMID 37500691, 2023). "Furthermore, another study has pointed out that treatment with Progesterone (a pleiotropic steroid hormone) in GBM cells can exert anti-tumor properties and suppress glycolysis and Warburg’s effect via inhibiting GLUT1, GAPDH, and cytoplasmic activity of FOXO1." (PMID 37821870, 2023). "Considering that the active PI3K signaling pathway in tumor cells destabilized FOXO1 protein, we treated MCF7 and MDA-MB-231 cells with the phosphatidylinositol-3-kinase (PI3K) inhibitor, LY294002, and found that the expressions of FOXO1 protein and CYP1B1-AS1 were up-regulated." (PMID 37640964, 2023). "Indeed, IHC staining showed that the levels of p21 and Foxo1, two tumor suppressors were increased substantially, whereas the levels of p27 and Nrf2 were not elevated in Rbx1‐null tumor tissues." (PMID 37470067, 2023). "Analysis of miR-182-5p, Cyld and Foxo1 expression levels, based on datasets from human HCC samples, showed results consistent with those from our mouse models, and also highlighted the ability of miR-182-5p to distinguish between normal and tumor tissues (AUC 0.83)." (PMID 37298191, 2023). "However, tumors grew faster when CPEB3 was silenced and the tumor-promoting action was not suppressed by miR-9-5p silencing and FOXO1 overexpression." (PMID 35805200, 2022). "Moreover, our ChIP-Seq analysis reveals that the annotated gene regulatory regions of the other 3 TFs were highly overlapped with those of FOXO1, suggesting that their coordinated activity is necessary for establishing MCL transcriptional identity and supporting tumor cell survival." (PMID 36282572, 2022). "However, for patients P18 and P25, who showed to be PAX3-FOXO1-positive by mRNA capture sequencing, two independent FOXO1 break-apart FISH analyses (performed at different pathology departments) demonstrated 0% positive tumor cells." (PMID 36232302, 2022). "FOXO1/3 and SMAD3 pathways could promote the tumor development." (PMID 35017463, 2022). "In an address to transcription factor-independent activity of FOXO1, our findings indicate a 2.66-fold (p<0.0001) significant decrease in mRNA level of FOXO1 in PTC compared to normal adjacent (control) tissues suggesting an overall insufficiency in the related tumor suppressor pathways." (PMID 36777002, 2022). "From these results, we suggest that nuclear FoxO1 is an important transcription factor that induces ESM-1 expression; however, the increased cytosolic FoxO1 level in tumor cells may be correlated with tumor progression." (PMID 36077661, 2022). "Regressed tumor growth was observed in a xenograft nude mouse model after transplantation of FoxO1-expressing cancer cells but not after transplantation of FoxO1-expressing cancer cells upon a stable knockdown of Atg7, demonstrating that FoxO1 exerts tumor-suppressor activity by inducing ACD43." (PMID 32591647, 2020). "In HepG2 tumor tissues treated with HDIs, FOXO1 and ULK1 expression was significantly elevated compared with the control group, but when mice were treated with HDIs combined with AS, FOXO1 and ULK1 expression in tumor tissue was significantly reduced to levels close to that of the control group." (PMID 32929346, 2020).
tumor (continued). "In support of a tumour-suppressive role for FOXO acetylation, a report shows that the acetylation recruits FOXO1 to promyelocytic leukaemia (PML) protein in the nucleus to protect FOXO1 against ubiquitination and to promote its activity in pancreatic beta cells." (PMID 32372224, 2020). "Thus, Akt-mediated phosphorylation of FoxO1 appears to be a mechanism to block FOXO1 tumor suppressor function in the nucleus and to activate a non-genomic tumor suppressor function of FoxO1 resulting in inhibition of the MAPK cell survival pathway." (PMID 30646603, 2019). "In the current study, we used anti-CCL20 antibody to investigate tumor growth in vivo and found that blockade of CCL20 suppressed tumor progression and restored 5-FU sensitivity in CRC, suggesting that the FOXO1/CEBPB/NF-κB/CCL20 axis may be a potential therapeutic target for CRC." (PMID 31395078, 2019). "Surprisingly, we found that FOXO6, but not FOXO1, 3, and 4, was frequently overexpressed in breast cell lines and tumours compared to normal cells, suggesting that this FOXO gene could act as an oncogene in human breast carcinogenesis." (PMID 29484124, 2018). "In a B16-OVA tumor model, IL-7-treated OT-II Th9 cells were found to mount potent antitumor activity, which is suppressed in the absence of Foxo1, suggesting that Foxo1-mediated IL-9 induction is essential in mounting the potent antitumor immunity by Th9 cells." (PMID 29867972, 2018). "However, the miR-370-induced reduction in tumor volume was not correlated with the miR-370-induced reduction in FOXO1 or TGFβ-RII expressions." (PMID 30497054, 2018). "Furthermore, inhibition of NFκB by genetically ablating its activating kinase inhibitor, IKKβ, by conditional deletion in a mouse model harboring the Pax3:Foxo1 chimeric oncogene failed to abrogate spontaneous tumor growth." (PMID 28883017, 2017). "In the annual fish, resveratrol down-regulated acetylation of K-Ras, phosphorylation of FoxO3a, acetylation of FoxO1 and phosphorylation of DLC1 by SIRT1 or SIRT1-mediated inactivation of K-Ras/PI3K/AKT signal, and inhibited cell proliferation and promoted cell apoptosis in spontaneous neoplasms." (PMID 28903430, 2017). "In the second tumor, the deleted region contained FOXO1 but not RB1." (PMID 28193293, 2017). "In conclusion, our results demonstrated that 16 miRNAs were able to correctly classify tumors into tumor subtypes (PAX3/FOXO1-positive ARMS and translocation-negative RMS) and may be useful to diagnose RMS." (PMID 25915942, 2015). "Moreover, FoxO1-negative cells formed tumor spheres in culture and developed tumors after serial adoptive transfer into NOD/SCID mice, while the FoxO1-positive cells did not." (PMID 26068418, 2015). "Finally, both tumor sphere formation, tumor formation after serial adoptive transfers and studies of selective elimination of FoxO1-negative population all supported that FoxO1-negative cells are CSCs in PDAC." (PMID 26068418, 2015). "We put FoxO1-negative and FoxO1-positive cells into the tumor sphere media (TSM)." (PMID 26068418, 2015). "Interestingly, although FOXO1 is frequently repressed in different tumor types, promoter hypermethylation has never been observed by other studies." (PMID 24977668, 2014). "In addition to NRs, an important non-NR partner of PGC-1α, FOXO1, was found to be down-regulated in tumor tissue." (PMID 25141867, 2014). "Similarly, Zhao and colleagues demonstrated that the transcription factor FoxO1 promotes autophagy in a manner independent of its transcriptional activity and induces autophagic cell death in tumor cells, suppressing tumor growth of xenografts in nude mice." (PMID 25328887, 2014). "Given the fact that PGC-1α and FOXO1 are essential coactivators of HBV transcription, we hypothesize that down-regulation of these genes may contribute to the sudden and significant decrease of HBsAg expression that we documented in the tumor." (PMID 25141867, 2014).
tumor (continued). "Furthermore, many structurally uncharacterized Ets domain interactions involve other TFs central to cellular development or neoplasia, such as the androgen receptor, HOX homeodomains and forkhead TFs, although an ETS1–FOXO1 (forkhead box O1) structure (PDB code 4LG0) is currently on hold in the PDB." (PMID 24450640, 2014). "To investigate the transcriptional basis of this Pax3:Foxo1a dynamic expression, we performed QPCR of Pax3 and Foxo1 using cell cycle specific sorted C2C12 mouse myoblast cells of the genotype Pax3(wt/wt) and mouse aRMS primary tumor cells of the genotype Pax3(wt/Pax3:Foxo1a)." (PMID 24453992, 2014). "Indeed, the immunoblots confirmed the upregulation of FOXO1 and RAG1 in FARSAKD Jeko cells, and overexpression of FARSA in Jeko and REC1 cells reversed their expression levels, thus supporting another activated tumor-promoting FOXO1-RAG1 signaling in the FARSA-manipulated MCL cells." (PMID 36675119, 2023). "However, it has been shown that FOXO1 but not FOXO3 mediates the tumor-inhibiting effect of CR." (PMID 37891184, 2023). "Similarly, AQP3 had a lower expression in FOXO1-transfected SUM159PT (SUM159PT-FOXO1+) xenografts than in the control SUM159PT cells, and such an opposite relationship was also observed in in vivo mouse tumor samples after CAP treatment but with elevated AQP3 intensity." (PMID 35637961, 2022). "Importantly, we observed that PPARγ activation in the tumor tissues was in line with the expression of the target gene PTEN, but inversely correlated with the activation of Akt, as indicated by the phosphorylation of Akt (Ser473) and its downstream FoxO1 (Ser256) and Bcl2 (Ser70)." (PMID 30845932, 2019). "Although other inflammatory responses induced by TPA were mostly reduced in response to CR, even in Foxo1+/− CR mouse skin (data not shown), reduction of FoxO1 in the CR condition might affect the regulation of prostaglandins formation and then impair the tumor-inhibiting effect of CR." (PMID 31888201, 2019). "We did not observe a correlation between the expression of SRC-3, ErbB-2, hTERT, PTEN, FoxO1, Bcl-2, SMAD4, c-myc, Hsp70, Hsp90 and CHIP expression in BxPC-3 cells, this result could be explained by feedback of complicated signaling network in different tumor environments." (PMID 24722501, 2014). "Specifically, MYC showed positive correlations with oncogenic factors HDAC2, HDAC3, AKT2, and AKT3, while demonstrating negative correlations with tumor suppressors PTEN and FOXO1." (PMID 40229260, 2025). "Our unsupervised analyses of DNA methylation patterns in these GEMM tumours yielded two major clusters, corresponding to high and no/low expression of Pax3::Foxo1, which mirrored the results for human FP and FN RMS tumours." (PMID 39812007, 2025). "Notably, and unlike PAX3::FOXO1-driven tumors, tumorigenesis was significantly more efficient in P0 animals, where even the fusion alone (+ sg-empty) led to tumors with 100% penetrance, albeit with mean latencies of about 230 days and 37% bilateral tumor fraction." (PMID 40523919, 2025). "Foxo1fl/flCD4Cre+ mice have the FOXO1 gene selectively deleted in CD4+ T cells, allowing us to investigate the T-cell-specific role of FOXO1 in tumor progression with or without a high Zn diet." (PMID 39247196, 2024). "An alternative interpretation posits that FOXO1, rather than TCF1, is mainly responsible for endowing tumour-reactive T cells with a stem-like or progenitor phenotype, and that TCF7 expression is merely a readout for FOXO1 activity." (PMID 38600391, 2024). "Integrating genes that exhibit a negative correlation with tumour cell MOMP activity and the pan‐cancer immunotherapy CRISPR screening results, FOXO1 emerged as the core TF involved in promoting immune resistance." (PMID 38899748, 2024). "FOXO1 overexpression, but not TCF7 overexpression, also significantly reduced expression of the exhaustion markers PD-1 and TIM3 on tumour-infiltrating CD8+ CAR T cells, whereas Ki-67 expression was unchanged." (PMID 38600376, 2024).
tumor (continued). "Enhanced infiltration of FOXO1-overexpressing CAR T cells was also observed at day 7 post-treatment, when control CAR T cells were almost absent from the tumour site." (PMID 38600376, 2024). "Whole-genome sequencing of tumor and normal somatic pairs revealed genotypes of RMS that are characterized by the fusion of PAX3 or PAX7 with FOXO1 (PAX-FOXO1) or those without these fusions." (PMID 37664028, 2023). "Reversible inhibition of ATP production and durable suppression of PTC growth indicates that the downregulation of mitochondrial function has a negative impact on tumor progression and LNM via the PI3K/Akt/FoxO1/Cyclin D1 pathway." (PMID 35865479, 2022). "Indeed, studies have found that TAMs can induce the expression of FOXO1 protein in gastric cancer cells, thus promoting EMT, invasion, and metastasis of tumor cells, which indicates that FOXQ1 repression in tumor cells may be the key to inhibiting tumor metastasis." (PMID 33224886, 2020). "ENT as a single agent showed minimal antitumor activity in this embryonal model of RMS; however, in these fusion-negative (Pax3:Foxo1 non-expressing) mice, treatment with the combination of ENT plus VCR reduced tumor volume significantly." (PMID 31113472, 2019). "This tumour was fusion negative, showing increased copy number (up to 10 per cell) for PAX3, PAX7 and FOXO1 and displaying TFAP2B positive reaction." (PMID 31493794, 2019). "Unlike FOXO1, the FOXM1 protein is upregulated by EWS-FLI1 and serves as an oncogenic mediator that results in tumor proliferation; a reduction of FOXM1 protein results in decreased anchorage independent growth." (PMID 31275859, 2019). "In an inducible PAX3::FOXO1 human myoblast system, the fusion-oncogene cooperated with MYCN to inhibit differentiation and promote proliferation during transformation; however, in this context, PAX3::FOXO1 is not required for tumor recurrence." (PMID 40599857, 2025). "This was despite the fact that the frequency of FOXO1-expressing CAR T cells was not increased in the spleen at this timepoint, indicating that FOXO1-expressing CAR T cells were more likely to traffic to the tumour site." (PMID 38600376, 2024). "Indeed, overexpression of FOXO1, but not TCF7, significantly enhanced control of tumour growth relative to control CAR T cells." (PMID 38600376, 2024). "We identified that FOXO1 directly regulates CPEB3 transcription by ChIP-Seq assays, Western blot and luciferase reporter in HepG2 cells, although the regulation was not significant in Bel7402 cells and tumor tissues (right)." (PMID 35805200, 2022). "At 100 mg/kg bw/day, BPAF resulted in the significant upregulation in gene expression of seven targets (GPER1, JNK, Akt, Fos, FOXO1, PDZK1, SRF), while the gene expression of the other 12 targets were not significantly changed compared to the SK-BR-3 bearing tumor control." (PMID 36497816, 2022). "With IL-2 and resveratrol co-treatment, the expression levels of FoxO1 were not different from the resveratrol treatment alone, which suggest that IL-2 does not directly affect the expression of FoxO1 in B16F10 tumor cells." (PMID 22532866, 2012). "Finally, we used 18 paired CRC patient specimens in the CRC tissue array to demonstrate that the expression of FoxO1 in the nuclei was significantly lower in tumor specimen and the miR-449a target genes LEF-1 was highly expressed in the tumor parts compared to the non-tumor parts." (PMID 34737955, 2021). "In the tumor microarray data, 1,693 probe-sets (1,115 upregulated and 578 downregulated) on the HG U133A platform were either significantly upregulated or downregulated in the PAX3(+/−Q)-FOXO1-positive ARMS tumors (n=16) compared to the fusion-negative ERMS tumors (n=15)." (PMID 23733015, 2013).